LEF1 (lymphoid enhancer binding factor 1)
Diseases named in the same sentence as LEF1 in open-access papers (continued):
Sharing a sentence is not in itself a finding about the gene and the disease.
tumor (continued). "Notably, IGF2BP1-controlled LEF1 expression could be validated by loss- as well as gain-of-function analyses and was observed in all mesenchymal-like tumor-derived cells analyzed in this study." (PMID 23677615, 2013). "LEF1 is a key transcription factor in the Wnt/β-catenin signaling pathway and plays a critical role in various tumor types." (PMID 40810004, 2025). "Similar to β-catenin, accentuated LEF1 staining was observed in myoepithelial cells surrounding the tumor nests, with clear nuclear expression." (PMID 39881334, 2025). "CD99 and LEF1 inversely correlated with tumor size and proliferative activity (Ki-67), whereas Cyclin D1 and Ki-67 positively correlated with tumor size and lymphovascular invasion (LVI)." (PMID 40307756, 2025). "Among the commonly upregulated genes, the transcription factor LEF1 was significantly expressed in both tumor types." (PMID 39851951, 2025). "Based on the H-score, weak nuclear staining for LEF-1 was observed in 20 (35%), intermediate staining in 17 (29%) and strong staining in 21 (36%) out of 58 tumours." (PMID 40130164, 2025). "Immunohistochemical staining was identified positive (nuclear staining of LEF1 and β-catenin in > 50% of tumor cells)." (PMID 39881334, 2025). "HMGA2, a chromatin remodeling protein, is known to promote cellular plasticity and stemness, potentially synergizing with LEF1-driven WNT activation to enhance tumor aggressiveness." (PMID 39851951, 2025). "Although the interaction between cells in the tumor microenvironment is complex, we propose that LEF1‐expressing CAFs contribute to the proliferative potential of cancer cells and their ability to undergo transdifferentiation into SCC." (PMID 39887653, 2025). "Other potential limitations include assessing for pLoF in oncogenic candidates such as RET, ROS1, FGFR4, and MYC, while FAT1 and LEF1 reported to oscillate between oncogenic and tumour suppressive behaviour." (PMID 41038821, 2025). "At RNA level, tumours with high LEF-1 expression showed significant downregulation of 37 transcripts (including 8 involved in antigen presentation)." (PMID 40130164, 2025). "Our findings of the involvement of LEF1‐expressing CAFs in the tumor growth promotion and squamous cell carcinogenesis will expand the understanding on the significance of cancer cell–stromal cell interaction in cancer malignancy." (PMID 39887653, 2025). "Within the nucleus, USP30 acts as a tumor suppressor by deubiquitinating LEF1 at K379/K382, disrupting the β‐catenin/LEF1 transcriptional complex and inhibiting cancer stemness, chemoresistance, and metastasis in TNBC." (PMID 41306556, 2025). "Depleting LEF1 resulted in reduced xenograft tumor growth, accompanied by decreased cancer‐cell proliferation and angiogenesis in the tumors." (PMID 39887653, 2025). "We did not observe any significant differences in the composition of T cell subtypes between tumours with low, intermediate and high LEF-1 expression." (PMID 40130164, 2025). "With positive predictive values of 95% for PA and 97% for BCC, respectively, a positive LEF1 result indicates a benign tumor; further IHC studies with LEF1 are needed." (PMID 39834626, 2025). "This leads to an increase in LEF1 activity within the tumor cells, driving Malignant_EP_04 cells to undergo EMT and transdifferentiate into SFRP4+ CAFs." (PMID 40810004, 2025). "Tumor cells are reactive to smooth muscle actin (SMA), beta-catenin, lymphoid enhancer-binding factor 1 (LEF1), and cyclin D1, and it is associated with catenin beta-1 (CTNNB1) mutation." (PMID 41246587, 2025). "To gain a deeper understanding of how LEF1 depletion in exp‐CAF 544 cells led to the suppression of xenograft tumor, we conducted RNA‐seq analysis to compare the gene expression profiles of 544‐shCtrl and 544‐shLEF1s (shLEF1‐1, ‐3, and ‐9)." (PMID 39887653, 2025). "Overall, these data are consistent with the idea that aberrant LEF1 expression in 544 cells contributes to xenograft tumor proliferation." (PMID 39887653, 2025).
tumor (continued). "LEF1 is frequently highly expressed in tumor development, potentially driving cancer proliferation and spread." (PMID 39200196, 2024). "We observed distinct regions of HNF4A+ cells and LEF1+ tumor cells, but also LEF1+ clusters that were interspersed with HNF4A+ clusters, as illustrated in PT13." (PMID 39567475, 2024). "For instance, in some tumor tissues, LEF1+ and HNF4A+ clusters were diffusely intermixed, whereas they were more separated in others." (PMID 39567475, 2024). "Decreased Lef1 expression/Re-sensitized tumor cells to docetaxel/Downregulated ABCG2, Vim and Cav1 expression." (PMID 39712006, 2024). "The presence of HNF4A+ and LEF1+ tumor clusters was generally consistent with the mixed embryonal and fetal histological classification made by the pathologist (R.R.d.K.)." (PMID 39567475, 2024). "Our previous research showed that FOXO4, IRF8, and LEF1 were differentially expressed (via RNA sequencing) in canine OSA compared to patient-matched non-tumour tissue." (PMID 38792023, 2024). "In contrast, the central memory T cell (Tcm) cluster was represented by cells expressing TCF7, ANXA1, LEF1, and SELL genes and is commonly associated with central memory and tumor inhibition function." (PMID 37615858, 2024). "We were able to identify tumor cells that stained strongly for either HNF4A or LEF1, with the staining pattern of the two TFs being mutually exclusive." (PMID 39567475, 2024). "Different levels of LEF1 and KDM4A enrichment were observed in the promoter regions of the selected genes implicated in tumour suppression or promotion." (PMID 37553362, 2023). "Although TGF-signalling is associated with cancer suppression in the early stages of tumour development, in late-stage tumours it exerts oncogenic function partially through inducing EMT-related factors such as Snail, Slug, ZEB1, ZEB2 and LEF1." (PMID 37239035, 2023). "A tumour-specific upregulation of Lef1 and Tcf7 genes was observed, as well as downregulation of Tcf7l1, while Tcf7l2 expression was unaltered." (PMID 37907668, 2023). "HE staining and immunohistochemistry staining for Ki67, CTNNB1, and LEF1 was performed to measure their expression levels in tumor tissues." (PMID 37740194, 2023). "We then isolated CD4+ T cells from the spleen, lymph nodes, and blood of healthy mice and tumor-bearing mice and investigated the expression of Tcf7, Lef1, and Axin2." (PMID 36239683, 2023). "Online miRNA target prediction database (Targetscan) was used to identify potential miR-371b-5p target genes, we identified both probable miR-371b-5p binding sites in Smad2 and LEF1, two positive regulators of tumor progression." (PMID 37106379, 2023). "The tumour volume of each group was calculated and analysed, demonstrating that LEF1/KDM4A promoted the growth of established tumour xenografts." (PMID 37553362, 2023). "All 10 DEGs found in the patients who lived in Sao Paulo city compared to the MRSP were associated with cell proliferation and tumor development (BMP4, CTNNBP1, DISP1, DVL1, ERBB4, PRLR, WNT5b, LEF1, PGR, and PTEN)." (PMID 36768749, 2023). "Our results demonstrate that LEF1 can undergo LLPS with β-catenin when Wnt/β-catenin signaling is activated in tumor cells." (PMID 37657935, 2023). "In GEO cohort, AXIN1 and LEF1 were highly expressed in tumor tissues, while FZD4 and FZD2 were highly expressed in normal tissues." (PMID 36703749, 2022). "LEF1 can promote tumor cell metastasis by participating in epithelial–mesenchymal transition (EMT) and manipulating intracellular reactive oxygen species (ROS)." (PMID 36419887, 2022).
tumor (continued). "LEF1 expression was positively correlated with tumor size, advanced tumor stage, and the number of tumorous lesions." (PMID 35110542, 2022). "Taken together, our data demonstrate that LEF1 impacts the developmental trajectory of E2a-/- T cell progenitors and can act as a tumor suppressor or oncogene depending on its availability during the transformation process." (PMID 35371057, 2022). "β-catenin plays an essential role in tumor cell proliferation, and LEF1 cooperates with β-catenin to accelerate tumor development." (PMID 35408897, 2022). "We found that AXIN1, CTNNB1 and LEF1 were highly expressed in tumor tissues and FZD4 was highly expressed in normal tissues in TCGA cohort." (PMID 36703749, 2022). "qRT-PCR analysis identified elevated expression of β-catenin target genes Axin2 and Lef1 in EdarTg951/951 tumour tissue, as well as elevated Edar transcript abundance when compared to untransformed EdarTg951/951 mammary tissue." (PMID 34916592, 2022). "Further comprehensive analysis revealed that the expression of BCL2, LEF1, PLK1, and BNIP3 was correlated with tumor mutation burden, microsatellite instability, drug sensitivity, and pathology stage." (PMID 35251139, 2022). "This epigenetic alternation is expected to drive tumor proliferation by enhancing β-catenin signaling by silencing LEF1 expression." (PMID 35408897, 2022). "For P3 and P8, who only had progressive tumor and CTC samples, the driver genes EGFR with p.L858R mutation and LEF1 of the Wnt signaling pathway were detected, respectively, in both CTCs and progressive tumors of each patient." (PMID 34616428, 2021). "In contrast, ten tumours showed a diffuse or patchy overexpression of LEF1 in addition to that present at the invasive front." (PMID 34420090, 2021). "Our results lead us to conclude that the expression of Lef1 in Apc-deficient epithelial cells blunts tumor initiation and growth by restricting MYC activity and the number of tumor-associated ectopic crypts that provide niches for tumor stem cells." (PMID 34788095, 2021). "Aberrant expression of m6A methyltransferase METTL3 increased m6A methylation and total mRNA level of LEF1, resulting in the activation of Wnt/β-catenin signaling pathway and accelerated tumor progression." (PMID 35186011, 2021). "To study the ability of the Apc;Lef1-deleted tumor cells to form organoids in culture, we isolated intestinal cells from LApc and LApcL mice 21 days after tamoxifen treatment and cultured them in growth factor–deficient Matrigel." (PMID 34788095, 2021). "LEF1 nuclear expression was observed in 92 (44.4%) out of 207 cases and an Allred score of ≥ 3 was observed in 75 (36.2%) tumours." (PMID 34420090, 2021). "Lef1 deletion in all intestinal epithelial cells led to a substantial decrease in the survival of ApcMin/+-mutant mice due to an increased tumor burden throughout the gut." (PMID 34788095, 2021). "Removal of Cbx3/HP1γ restraint allows CD8+ T cells to become effector-like cells armed with an intrinsic heightened killing and persistence capacity to control tumor growth; LEF-1 function and IL-21R signaling are necessary." (PMID 34721405, 2021). "Upregulated miR-449a suppresses CRC tumorigenesis including cell proliferation, migration, invasion, and tumor formation by silencing the expression of target genes Cyclin D1 and LEF-1 at the translational level." (PMID 34737955, 2021). "Wilms’ tumor 1 (WT1), a tumor-suppressor gene, can interact with lymphoid enhancer-binding factor 1 (LEF1) to mediate Wnt signaling activation." (PMID 34926267, 2021). "Consistent with the effect of LEF1 OP‐V1 on tumor growth, LEF1 OP‐V1 treatment decreased LEF1 protein and inhibited LEF1/β‐catenin target gene expression in tumors." (PMID 34397171, 2021). "To analyze Lef1 function in tumor development, we conditionally deleted Lef1 in intestinal stem cells of Apcfl/fl mice or broadly from the entire intestinal epithelium of Apcfl/fl or ApcMin/+ mice." (PMID 34788095, 2021).
tumor (continued). "The inability of Lef1-, Il21r-, Cbx3-Lef1- and Cbx3-Il21r-deficient CD8+ T cells to halt tumor development suggests that LEF-1 and IL-21R are necessary for their persistence in tumors." (PMID 34721405, 2021). "The increased/sustained expression of LEF-1 and IL-21R together with the enhanced effector capacity exhibited by Cbx3/HP1γ-deficient CD8+ effector T cells suggest they can persist to control tumor development." (PMID 34721405, 2021). "As expected by the increased tumor burden in the LApcL intestine, we found an expansion of blood and lymphatic vasculature after Lef1 deletion, indicating participation of the stromal microenvironment in the increased tumor growth." (PMID 34788095, 2021). "Lef1 is induced in intestinal adenomas, in which it restricts ectopic crypt formation and tumor growth." (PMID 34788095, 2021). "When Wnt ligand secretion is prevented in such tumors, Lef1 cells start to die and are eliminated from the tumor." (PMID 34849464, 2021). "Extracellular matrix-associated gene expression is also correlated with TCF7L1 specifically in normal tissue and with LEF1 expression exclusively in tumor tissue." (PMID 32403323, 2020). "Combined with the increase in DKK3 and MMP3 expression seen in tumor tissue, the demonstration of aberrant activation of LEF1 in the current study adds OSA to the range of cancers that exhibit aberrant Wnt activity." (PMID 32854182, 2020). "Comparison between these two, i.e. between TCF7L1- and LEF1-correlated transcription, also reveals a potential correlation of LEF1 expression with double strand break DNA repair in tumor." (PMID 32403323, 2020). "Since LEF-1 has been related to tumor progression to metastasis and this gene has been reported to be regulated for ERG, we measured it’s expression in VCaP cells after treatment with exogenous SFRP1." (PMID 32694934, 2020). "In total, 16 cases were tested for LEF1 and all were positive in the tumor cells, confirming the diagnosis of CLL." (PMID 32848129, 2020). "In summary, we determined miR-34a-5p as a tumor suppressor that can block the expression of LEF1, thereby inhibiting proliferation, migration, invasion, and EMT in ESCC." (PMID 32226522, 2020). "PPARγ inhibited tumor proliferation and metastasis by inhibiting LEF1/β-catenin signaling, and the expression of PPARγ in UC after RT decreased significantly." (PMID 33289586, 2020). "Next, a tumor sphere formation assay was used to explore the effect of LEF1 on CSC self-renewal properties in ESCC." (PMID 31296250, 2019). "Increased expression of Wnt5a and Fzd1 and decreased expression of Lef1 and Camk2a were validated in different tumor samples by quantitative PCR." (PMID 30670683, 2019). "Studies have been conducted to directly regulate the expression of LEF1 by miRNAs, mainly focusing on tumor diseases." (PMID 31753039, 2019). "Correlation of IRS values for TCF1 and LEF1 revealed significant positive correlation between the two proteins across all tumour grades (rs = 0.474, df = 92, P < 0.001)." (PMID 30468298, 2019). "For example, collagen type I in the adjacent ECM has been implicated in promoting EMT through numerous mechanisms, including upregulation of NFκB, Snail, and lymphoid enhancer-binding factor-1 (LEF-1) in tumor cells." (PMID 31788448, 2019). "Increased expression of Tcf7, and its co-operating transcription factor Lef1, were further confirmed by quantitative PCR analysis in different EμMyc/Casp2−/− tumor samples." (PMID 30670683, 2019). "As the high OCT4 and LEF1 expression levels in 95 patients with ECSS showed a correlation with tumor pathogenesis and poor clinicopathological characteristics, we further explored the relationship between OCT4 and LEF1 in vitro." (PMID 29974668, 2018).
tumor (continued). "Consistently, inhibition of tumor growth by ESRRG overexpression in a xenograft mouse model was rescued by the re-introduction of TCF4/LEF1, and Ki67 expression was also rescued." (PMID 29765046, 2018). "Slit/Robo signalling has been shown to interact with the Wnt/β-catenin signalling in different types of tumour cells, and we found here that Robo1/2 KO pancreatic cells exhibit a reduced level of Axin2 expression but Lef1 appeared unchanged at E12.5." (PMID 30504829, 2018). "In this scenario, tumor cells with activated EpCAM i.e. the released EpICD associates with FHL2, β-catenin which form a nuclear complex with Lef-1 and induces transcription of genes associated with cell proliferation." (PMID 28903370, 2017). "LEF1 serves as a transcriptional effector of the Wnt/β-catenin pathway and is critical for the tumor invasion induced by hepatocyte growth factor (HGF)." (PMID 28934958, 2017). "Our experiments show that LEF1 can function as a tumor suppressor in this tumor entity and suggest that LEF1 is possibly one of the major mediators of RMS differentiation." (PMID 27965462, 2017). "Together these data suggest that LEF1 rather has tumor suppressive functions and attenuates aggressiveness in a subset of RMS." (PMID 27965462, 2017). "Because of these context dependent effects, LEF1 can function as either an oncogene or a tumor suppressor." (PMID 27965462, 2017). "Despite high heterogeneity among patient samples and cell lines, our LEF1 knockdown experiments using Rh41, RMS-13 (ARMS) and TE671 (ERMS) cell lines demonstrate that LEF1 can reduce tumor progression and induce myodifferentiation." (PMID 27965462, 2017). "Immunohistochemical staining revealed that Smad4 and LEF1 were expressed in the nuclei of tumor cells." (PMID 27595937, 2016). "Lef1 and nuclear β-catenin were limited to Ecad-deficient/GLI2A-expressing mesenchymal-appearing tumor cells, establishing a strict relationship in these tumors between canonical Wnt signaling activity and EMT." (PMID 26859571, 2016). "To strengthen this assumption, we analyzed the expression of a further LEF responsive gene, LEF1, in the primary tumor and the metastases." (PMID 27825128, 2016). "As a key transcription factor of the Wnt/β-catenin pathway, LEF1 helps to regulate important genes involved in tumor cell death mechanisms." (PMID 26950276, 2016). "Adherent confluent Mel8 cells express higher level of WNT5a, TCF4 and VEGF and lower level of LEF1 at mRNA level than sub-confluent cells suggesting that these cells are prone to phenotype switch, simulating in vitro tumor spreading." (PMID 27175588, 2016). "Comparing papCP and adaCP tumor samples, the latter showed significant up-regulation of direct targets of the Wnt/β-catenin signaling pathway (LEF1 and AXIN2) as well as important components of the hedgehog signaling pathway (GLI2, PTCH1 and SHH)." (PMID 26927026, 2016). "In tumors containing larger regions of EMT, Lef1 was detected adjacent to epithelial tumor cells, suggesting activation of Wnt signaling early, and transiently, during EMT." (PMID 26859571, 2016). "To investigate the potential mechanism of Caco-2 cells and LoVo cells, we used PCR to examine the expression of mRNA in 19 genes including their difference in the tumor sample previously found and Axin1, LEF1, TCF4." (PMID 26214021, 2015). "It has been shown at least in tumor cell lines, that LFG expression is regulated by the Akt/LEF-1 pathway, conferring tumor cells resistance to apoptosis." (PMID 26565411, 2015). "Tumor-initiating cells show a constitutive activation of this pathway, which can be evaluated by the LEF-1/TCF dGFP reporter." (PMID 25537513, 2015).